EGFR (epidermal growth factor receptor)
Diseases named in the same sentence as EGFR in open-access papers (continued):
Sharing a sentence is not in itself a finding about the gene and the disease.
psoriasis (continued). "As has been proposed previously, EGFR signaling may be a significant and integral component in the pathogenesis of Koebnerization and psoriasis." (PMID 31936670, 2020). "The EGFR-ERK/JNK-CCL20 pathway in scratched keratinocytes may explain why Koebnerization is frequently seen in psoriasis patients." (PMID 31936670, 2020). "In addition, NE proteolytically activates the epidermal growth factor receptor (EGFR) signaling pathway resulting in excessive keratinocyte proliferation in psoriasis." (PMID 31649677, 2019). "Moreover, khellin and visnagin have been used in the photo-chemotherapeutic treatment of vitiligo and psoriasis, photoreaction with DNA and Khellin displayed important epidermal growth factor receptor (EGFR) inhibitory activity." (PMID 30373270, 2018). "Single nucleotide polymorphisms (SNPs) involved in miRNAs that can regulate the expression of EGFR could potentially influence the development of psoriasis." (PMID 25209759, 2014). "Indeed, EGFR inhibitors improve lesions in patients with psoriasis, as also shown in skin lesions of K5.Stat3C mice in the present study." (PMID 25384035, 2014). "In addition, several in vitro experiments referring to the function of rs2910164 SNP in keratinocytes and EGFR regulation were also performed to elucidate its functional relevance with the development of psoriasis." (PMID 25209759, 2014). "EGF receptor (EGFR) ligands, including heparin-binding EGF-like growth factor (HB-EGF), amphiregulin and transforming growth factor (TGF)-α are also TACE substrates and are psoriasis-associated growth factors." (PMID 25384035, 2014). "Considering the fact that EGFR is overexpressed in psoriasis, the up-regulation of miR-146a may be a protectively negative feedback factor in psoriasis." (PMID 25209759, 2014). "Tyrphostins that specifically target EGFR may also lead to improvements of skin conditions in patients with psoriasis." (PMID 24170986, 2013). "Furthermore, vitamin D, a drug used in the treatment of psoriasis, downregulates EGFR and cyclin-D1." (PMID 19551138, 2009). "While there are no previous studies in current literature confirming the relationship between EGFR expression in PD patients’ keratinocytes, it is well-established that altered EGFR signaling plays a role in various dermatological conditions, including psoriasis." (PMID 40405084, 2025). "Interestingly, EGFR inhibitors used in cancer therapy have been reported to alleviate psoriatic symptoms, further underscoring the therapeutic relevance of this pathway in psoriasis management." (PMID 41471291, 2025). "In summary, our findings suggest that EGF may significantly dampen the IFN-γ-induced transcriptome in keratinocytes, including genes involved in leukocyte trafficking, antigen presentation, and tissue inflammation upregulated in autoimmune diseases like psoriasis and by EGFR inhibitors." (PMID 39924511, 2025). "Therefore, rs726365708 might be a useful genetic marker to detect ERRFI1 activity and the level of EGFR-TKI resistance, enabling personalized clinical application of EGFR-TKIs for patients with cancer or psoriasis." (PMID 31969149, 2020). "Therefore, inhibitors with potent activity blocking signaling pathways of EGFR may have the potential to treat psoriasis." (PMID 31187048, 2019). "Moreover, a drug called SU5271 that inhibits the activity of EGFR has been verified to suppress the proliferation of keratinocytes in an initial clinical trial 9, which demonstrates that EGFR can act as a therapy target for psoriasis." (PMID 25209759, 2014). "Given the regulatory relation between miR-146a and EGFR as well as the important role of EGFR in the development of psoriasis, we have suggested that rs2910164 in miR-146a could potentially affect the miR-146a-mediated regulation on EGFR, thus leading to individual susceptibility to psoriasis." (PMID 25209759, 2014).
psoriasis (continued). "Some recent studies have suggested that epidermal growth factor receptor (EGFR), a cell surface protein that binds to epidermal growth factor, is overexpressed in psoriatic lesions 6 and contributes a lot to the hyperproliferation of keratinocytes in psoriasis 7,8." (PMID 25209759, 2014). "Therefore, rs2910164G allele in miR-146a may contribute to the increased expression of EGFR in psoriasis by down-regulating the level of mature miR-146a, which in turn induces the hyperproliferation of keratinocytes in psoriatic lesions." (PMID 25209759, 2014). "While EGFR has been verified target for miRNA-146a, another study identified FERMT1 as a psoriasis-related miRNA-146a target gene involved in keratinocyte proliferation." (PMID 41294623, 2025). "Therefore, we suggest that DcR3 and EGFR activation form a positive feedback loop and that DcR3 might mediate the regulatory functions of EGFR in keratinocyte differentiation, which might accelerate the pathogenesis of skin disorders such as psoriasis." (PMID 35478210, 2022). "In psoriasis, IL–6 production is increased, which synergizes TNF-α and IL–1 to advance the hyperproliferation of epidermis by its activity on epidermal growth factor receptor." (PMID 34947782, 2021). "TACE, in turn, can promote the occurrence of psoriasis by releasing mediators of psoriasis, including TNF-α and EGF receptor (EGFR)." (PMID 33975513, 2021). "TWEAK/Fn14 signaling contributes to the development of psoriasis by upregulating the TNFR2, EGFR, and keratin 17 expressions in keratinocytes and the IL-6 expression in DMECs." (PMID 30038329, 2018). "Epidermal growth factor receptor (EGFR), which is overexpressed in psoriatic lesions, has been proven to contribute to the hyperproliferation of keratinocytes in psoriasis." (PMID 25209759, 2014). "Treatment of K5.Stat3C mice with TNF-α or EGFR inhibitors attenuated the skin lesions, suggesting the roles of TACE substrates in psoriasis." (PMID 25384035, 2014). "Vascular endothelial growth factor (VEGF), one of the downstream molecules of EGFR and TNF signaling, plays a key role in angiogenesis for developing psoriasis." (PMID 25384035, 2014). "In contrast to the high levels of EGFR in the epidermis of psoriatic patients, it was found that soluble serum EGFR levels were decreased and soluble serum EGF was increased in patients with psoriasis as compared to controls." (PMID 40405084, 2025). "In psoriasis, TKIs targeting pathways like VEGFR and EGFR could be combined with IL‐23 or IL‐17 inhibitors to address not only inflammation but also pathological keratinocyte proliferation and angiogenesis." (PMID 40536117, 2025). "Moreover, EGFR signaling has been shown to promote CCL20 production in a variety of cancers as well as in keratinocytes from psoriasis patients." (PMID 38472446, 2024). "During the study period, 67 patients with unresectable advanced or recurrent CRC received anti-EGFR antibody drugs as cancer chemotherapy for the first time; none of them reported skin diseases, such as psoriasis or atopic dermatitis." (PMID 36045384, 2022). "Based on our epigenomic data, we postulated that during Aldara®-induced inflammation and psoriasis, JNK1 could act downstream of the EGFR pathway in epidermal cells." (PMID 33613525, 2020). "IL-17A also upregulated CCL20 production via EGFR activation and further potentiated scratch-induced CCL20 production, suggesting that epidermal CCL20 production is an integral part in the pathogenesis of psoriasis and Koebnerization." (PMID 31936670, 2020). "To assess whether EGFR signaling is involved in TPA-induced psoriasis-like skin lesions, we topically treated K5.Stat3C mice with AG1478, an EGFR inhibitor." (PMID 25384035, 2014). "Ultimately, KC activity in psoriasis is governed by stimulation of key membrane receptors, such as the glucocorticoid receptor (GR), G-protein coupled purinergic receptor P2Y (P2RY11) and epidermal growth factor receptor (EGFR)." (PMID 24260178, 2013).
psoriasis (continued). "Dual-tyrosine specificity phosphorylation-regulated kinase 1A (DYRK1A) is a key stabilizer of the epidermal growth factor receptor (EGFR) and plays a crucial role in cytokeratinization, hyperproliferation, aberrant differentiation, and inflammatory infiltration during the development of psoriasis." (PMID 40861221, 2025). "In psoriasis, miR-215 is reported to be downregulated in the skin lesion tissues in humans and mouse models, with the functional role validated in a keratinocyte-specific study, wherein miR-215 is shown to target DYRK1A and dysregulate keratinocyte proliferation via EGFR signaling." (PMID 37700769, 2023). "Similarly, EGFR signaling through MEK1/2 and p38 kinase synergizes with IL-1α in the skin innate immune response by enhancing the production of antibacterial peptides in normal skin and chronic inflammatory diseases like psoriasis." (PMID 23878744, 2013).
adenoma (58 papers, 1992 to 2025). A neoplasm arising from the epithelium. "EGFR signaling is needed for adenoma growth, and EGFR inhibitors cause regression of intestinal adenomas." (PMID 38609520, 2024). "It was previously shown that APC deficiency was associated with an increase in EGFR activity and c-Src expression in ApcMin/+ mouse adenomas and intestinal enterocytes." (PMID 34926717, 2021). "In FAP patients, EGFR has been found to be upregulated in most adenomas and carcinomas, with associated upregulation of downstream members of the signaling pathway." (PMID 34926717, 2021). "The USP8 mutation (14-3-3 somatic mutations) induces corticotroph EGFR adenoma signaling by rescuing EGFR from lysosomal degradation and enhancing EGFR accumulation." (PMID 31798535, 2019). "For the first time, characteristics of patients and adenomas were prospectively collected and analyzed by uni- and multivariate logistic regression to determine those that would be associated with EGFR overexpression in colorectal adenomas." (PMID 28157706, 2017). "By multivariate analysis in adenomas, associated factors with EGFR overexpression were HGD and tubulo-villous feature." (PMID 28157706, 2017). "Nevertheless, such genetic changes were less investigated in adenoma stage and a comprehensive survey of oncogenic mutations in EGFR signaling pathway according to different morphologic subtypes has not been performed." (PMID 25551625, 2014). "A total of 19 canine gastric epithelial neoplasms (5 adenomas and 14 carcinomas) were retrospectively evaluated for EGFR/HER-2 immunohistochemical expression and KRAS mutational status." (PMID 24454858, 2014). "In mouse models of chemical pulmonary tumorigenesis, in which the type of tumor is adenoma or adenocarcinoma, K-ras mutations are frequently observed, whereas genetic alteration of EGFR is generally rare." (PMID 24100939, 2013). "In animal studies, EGFR activity is elevated in the adenomas and has been associated with intestinal adenoma growth in ApcMin/+ mice." (PMID 24213116, 2011). "Moreover, compared with EGFR wild‐type malignant adenomas, EGFR‐mutated LCBM exhibit upregulation of multiple immune‐related pathways." (PMID 39712454, 2025). "The number of EGFR signaling-associatedlinks among the top and bottom 10% of the links in the order of linkweights is decreasing for the normal network (top, 42; bottom, 38),adenoma network (top, 27; bottom, 36), and carcinoma network (top,26; bottom, 32)." (PMID 33562960, 2021). "Although many studies have focused on the expression and function of EGFR in pituitary corticotroph adenomas, the association of EGFR with adenoma behavior, particularly the recurrence of pituitary corticotroph adenomas, was largely unknown." (PMID 31798535, 2019). "In particular, mouse adenomas are usually assumed to have only Apc mutations, whereas human CRCs often contain many genetic mutations, which might affect cellular responses to EGFR inhibition." (PMID 29872037, 2018). "Mutated USP8 adenomas harbor more EGFR expression, higher EGFR protein and higher POMC mRNAs." (PMID 29765354, 2018). "Additionally, the present study demonstrated that EGFR mutation rates were higher in adenoma and adenosquamous NSCLC compared with squamous NSCLC (P=0.001)." (PMID 26622815, 2015). "However, it remains unclear whether USP8 mutations and EGFR overexpression are associated with more aggressive adenomas." (PMID 34867776, 2021). "As a connection of EGFR with the pathogenesis of corticotroph adenomas has already been reported in both humans and dogs we hypothesized that the underlying mechanism for adenoma development might be similar in both species." (PMID 28005997, 2016). "Moreover, the expression of EGFR and its ligands is often elevated in tumors as compared to matched normal tissues and appears to be associated with malignant progression, with stronger expression in carcinoma than in adenoma." (PMID 24213116, 2011).
adenoma (continued). "In vivo images were collected from a spontaneous adenoma in the rectum of a live mouse using fluorescently-labeled peptides specific for Prdx1, EGFR, and ErbB2, respectively." (PMID 37945660, 2023). "The positive expression rates of EGFR were 0%, 0%, 8.7% (2/23), and 26.9% (7/26) in the control tissue, adenoma, EGC, and AGC, respectively (p = 0.003)." (PMID 35723316, 2022). "Immunohistochemistry for phospho-EGFR revealed markedly increased phospho-EGFR staining in Tspan6 mutant lung tumors, in particular in the hyperplastic regions and adenomas." (PMID 35184157, 2022). "Mechanistically, it has been reported that heterozygous deletion of ATG5 activated EGFR and Wnt/β–catenin pathways in adenomas of Apc(Min/+) mice leading to the enhancement of the IFN γ-dependent inhibition of these pathways." (PMID 33809172, 2021). "Although approximately 60% of pituitary adenomas, including ACTH-secreting adenomas (40%–80%) express EGFR, the role of the receptor in tumorigenesis remains under-investigated." (PMID 34295309, 2021). "Both neoplastic and normal pituitary tissues express EGFR and phosphorylated EGFR [pEGFR] and overall, NFPAs have higher EGFR, pEGFR expression than functional adenomas." (PMID 34295309, 2021). "Here, we investigated the expression profile of EGFR and its pathway signaling in pituitary corticotroph adenomas and its relationship to adenoma clinicopathological characteristics." (PMID 31798535, 2019). "Using this method, we hope to identify the clinical significance of EGFR, especially in predicting corticotroph adenoma recurrence." (PMID 31798535, 2019). "The initial adenoma progresses on to an intermediate adenoma when the epidermal growth factor receptor (EGFR) is activated, which in turn triggers the phosphatidylinositol-3-kinase pathway and results in tumour formation." (PMID 31234411, 2019). "In EGFR-overexpressing adenomas, the downstream pathway phosphorylated Erk (p-Erk) was also significantly activated." (PMID 31798535, 2019). "The knockdown of Egfl6 or expression of Lrig3 abolished the sensitivity of adenoma cells to EGFR inhibition." (PMID 29872037, 2018). "Vitally, our studies have also indicated a novel role for LGR5 expression in the sensitivity of adenoma cells to EGFR inhibitors such as gefitinib." (PMID 29149105, 2018). "Adenomas with HGD had an overexpression of EGFR (score ≥ 6) in 77.8% vs 10.0% in LGD adenomas (p < 0.0001)." (PMID 28157706, 2017). "The associated clinical, endoscopic and histological factors with EGFR overexpression (composite score ≥ 6) were assessed for adenomas by logistic regression." (PMID 28157706, 2017). "Adenomas with LGD had moderate (60%) to high (23.3%) intensity of EGFR expression, which is significantly higher than hyperplastic polyps that had a null to mild EGFR expression in 87.5% (p = 0.0015)." (PMID 28157706, 2017). "One gradient of EGFR expression was observed within the adenomas subgroup, and specifically across the grade of dysplasia: almost the half of LGD adenomas had a Goldstein grade 2-3 vs all of those in high grade dysplasia (HGD) (p < 0.001)." (PMID 28157706, 2017). "EGFR are early involved in colorectal carcinogenesis, and their expression is strongly correlated to the neoplasia stage, leading to validate EGFR as an interesting surface biomarker of adenomas." (PMID 28157706, 2017). "In contrast, in the present study there is a high rate of EGFR expression in adenomas whose size was mostly < 10 mm." (PMID 28157706, 2017). "Before to develop diagnostic nanoparticles bound to cetuximab (anti-EGFR antibody currently used in CRC), the level of EGFR expression on adenomas surface should be assessed and compared to normal colorectal mucosa or to other non adenomatous lesions." (PMID 28157706, 2017).